DLL4 (delta like canonical Notch ligand 4)
Diseases named in the same sentence as DLL4 in open-access papers (continued):
Sharing a sentence is not in itself a finding about the gene and the disease.
tumor (continued). "Endothelial JAG1 also antagonized DLL4 regulation of endothelial branching and increased vascular maturation downstream of DLL4-Notch1 in a skin wound healing model as well as promoted tumour growth through pro-angiogenic and angiocrine functions." (PMID 28445154, 2017). "Therefore, we analysed the effect of endothelial-specific versus ubiquitous Dll4 deletion on tumor proliferation." (PMID 28086833, 2017). "Previous studies have identified a role for DLL4 in tumor angiogenesis." (PMID 27891816, 2017). "Interestingly, DLL4 and Hey2 mRNA both had a 20-fold change difference in expression between the two tumor types." (PMID 28659656, 2017). "In addition, Dll4 is highly expressed in the tumor vasculature and is a negative regulator of tumor angiogenesis." (PMID 28117756, 2017). "The effects of DLL4-Notch signalling on stromal cells in tumour microenvironment may be greater than that of mJAG1-Notch signalling." (PMID 28445154, 2017). "Immunohistochemical staining for CD34 revealed that the treatment with anti-DLL4 mAb strikingly increased vessel branching in both EV- and mJAG1-tumours, suggesting a predominant role of DLL4 in the control of tumour angiogenesis and tumour growth in either EV-tumours or mJAG1-tumours." (PMID 28445154, 2017). "Indeed, endogenous DLL4 expression was higher in tumour vessels, particularly in those larger vessels which are known to have greater perfusion and more resistant to anti-VEGF therapy." (PMID 28445154, 2017). "In addition, Dll4 overexpression consistently improved tumor vascular maturation and functionality, as indicated by increased vessel calibers, enhanced mural cell recruitment and increased network perfusion." (PMID 28288569, 2017). "Importantly, anti-DLL4 antibody blocked the effect of JAG1 on tumour growth and increased vessel branching in vivo." (PMID 28445154, 2017). "However, we found that anti-DLL4 antibody was still capable of inhibiting tumour growth of both EV-tumour and mJAG1-tumour significantly." (PMID 28445154, 2017). "DLL4 expression highly correlates with tumor angiogenesis and metastasis." (PMID 27891816, 2017). "Delta-like 4 (DLL4) and Jagged1 (JAG1) are two key Notch ligands implicated in tumour angiogenesis." (PMID 28445154, 2017). "Therefore we intended to elucidate if Dll4 also regulates the fate of tumor stem cells beside its angiogenic effect in a spontaneous model of CRC, the ApcMin/+ mouse." (PMID 28086833, 2017). "Delta like 4 (Dll4)/Notch signaling is a key regulator of tumor angiogenesis." (PMID 28086833, 2017). "We tested the ability of gal-3 to interfere with JAG1 and DLL4-induced tumor growth." (PMID 28533486, 2017). "Enhanced DLL4 expression by mDLL4 was also found in tumour and stromal cells." (PMID 28445154, 2017). "Reports have shown that Dll4 inhibition delays the tumor growth by deregulating the tumor angiogenic process, but in CRC anti-DLL4 therapy may also reduce the cancer stem cell frequency." (PMID 28086833, 2017). "Thus our expression analysis indicates that in the ApcMin/+ small and large intestinal adenomas, Dll4 is the most upregulated ligand and is present both in the tumor epithelium and endothelium." (PMID 28086833, 2017). "Interestingly, in all these various types of tumor tissues, the DLL4 expression was significantly reduced compared to their normal tissue counterparts." (PMID 27542210, 2016). "Downregulation of the ligand DLL4 also slowed growth of the tumor cells." (PMID 27661116, 2016). "In cancer, Dll4 is most studied in relationship with tumor angiogenesis." (PMID 26766040, 2016). "Moreover, unlike some published reports, the results also show drastic down-regulation of DLL4 in cancer cell lines and all the tumor samples examined." (PMID 27542210, 2016). "Interestingly, Notch inhibition by silencing Dll4 in HepG2.2.15 led to cell cycle arrest at G1 phase in our study whereas GSI treatment of human non-tumor hepatic cell line L02 cells resulted in shorten S phase and increased apoptosis." (PMID 26766040, 2016).
tumor (continued). "Moreover, DLL4 blockade has been shown to improve the anti-tumor effects of VEGF inhibition in xenograft models." (PMID 27248821, 2016). "The upregulation of DLL-4 in the treated samples confirms its anti-angiogenic ability which is in compliance with the previous reports and resolves the contradictions relating notch signaling pathway and its effect in tumor angiogenesis." (PMID 26762567, 2016). "Of note, the disruption of Dll4/Notch signaling results in inhibition of tumor growth and was associated with excessive but non-productive angiogenesis and impaired tumor vessel perfusion." (PMID 26755662, 2016). "However, whereas Dll4 expression in tumors consistently affected the vascular phenotype, tumor growth was increased only in some tumors, probably due to differences in the vasculature and/or levels of endogenous components of the Dll4/Notch pathway." (PMID 26755662, 2016). "NOTCH3(+)CAFs may promote sprouting of tumor endothelial cells by a molecular mechanism similar to that of the DLL4/NOTCH1 pathway and stabilize the newly formed tumor vessels through JAG1/NOTCH3 interactions between endothelial cells and CAFs." (PMID 27124156, 2016). "While Dll4 mainly has a function in the vasculature, Jagged1 is important in immunosuppressive T regulatory cells and promotes the maintenance or expansion of hematopoietic precursor cells as well as tumor/stem cells." (PMID 26713603, 2016). "We observed that tumor-induced decrease in the expression of Notch receptors, Notch1, Notch2, Notch3 and Notch4, as well as ligands Dll1, Dll4 and Jagged1 in splenocytes of 4T1HA and RencaHA tumor-bearing mice could be reversed by treatment with bortezomib." (PMID 26431276, 2015). "Moreover, by up-regulation of Notch1 and VEGFR1, DLL4 played important roles in tumor angiogenesis and prognosis of lung cancer." (PMID 25996086, 2015). "The difference in the regulation of Dll4 in the tumor cells and vascular endothelium could be due to the tissue context, where miR-27b could cooperate with RNA binding protein(s), such as HuR causing mRNA stabilization and translational activation." (PMID 26161255, 2015). "However, despite the extensive characterization of the role of Dll4 in tumor vasculature, the contribution of other Notch ligands, like Jagged1, is less well studied." (PMID 26213336, 2015). "In addition, Dll4/Notch fundamentally participates in the regulation of embryonic, post-natal developmental, regenerative and tumor sprouting angiogenesis." (PMID 26314892, 2015). "The role of Dll4 differs in early and late tumor development." (PMID 26314892, 2015). "Blockade of the Dll4-Notch pathway in preclinical cancer models has been associated with non-productive angiogenesis and reduced tumor growth." (PMID 25393540, 2014). "Additionally, since Delta-like ligand 4 (Dll4)-activated Notch signaling is a major modulator of angiogenesis, anti-Dll4 agents are being investigated to reduce vascularization of the tumor." (PMID 25629006, 2014). "In a separate experiment, we tested whether Dll4 blockade in combination with continuous VEGF inhibition could also impair tumor growth in a sunitinib resistant PDX model." (PMID 25393540, 2014). "Dll4 expression is found to be extensive in the immature developing endothelium of neoplastic tissue, with low to undetectable levels in normal tissue, which constitutes the basis for the specific targeting of the tumor endothelium." (PMID 25393540, 2014). "Thus, the Dll4/Notch signaling pathway activation loop appears to promote tumor formation and progression." (PMID 25364440, 2014). "In addition, the associations among Dll4 expression levels, VEGF receptor-2 (VEGFR-2) expression levels and tumor progression in patients with CCRCC were assessed." (PMID 25364440, 2014). "All findings suggest that Dll4 expression is key in tumor angiogenesis, which indicates that D114 overexpression may be associated with poor prognosis in human cancer." (PMID 25364440, 2014).
tumor (continued). "Moreover, examination of 20 surgical GBM specimens yielded an upregulation of Dll4 both in GBM tumor cells as well as endothelial cells." (PMID 25601901, 2014). "Overall, these findings demonstrate the potent anti-tumor activity of Dll4 blockade in RCC patient-derived tumors and a combination benefit for the simultaneous targeting of the Dll4 and VEGF signaling pathways, highlighting the therapeutic potential of this treatment modality in RCC." (PMID 25393540, 2014). "In addition, the anti-tumor efficacy of anti-Dll4 and anti-VEGF combination therapy was also observed in a sunitinib resistant ccRCC model, which further highlights the great therapeutic potential of targeting these two pathways." (PMID 25393540, 2014). "Mouse Dll4 was robustly expressed in the stroma of RP-R-01 tumors, consistent with the function of Dll4 as a critical regulator of tumor angiogenesis, whereas the levels of tumor-cell expressed Dll4 (human) were very low, at the limit of detection." (PMID 25393540, 2014). "Mechanistically, tumor–derived VEGF induces DLL4 expression in sprouting endothelial cells (tip cells), which then provide signals to adjacent downstream Notch receptor–bearing endothelial cells (stalk cells) to down–regulate VEGF–induced sprouting and branching." (PMID 24931473, 2014). "Blockade of the Dll4-Notch pathway in preclinical cancer models results in non-productive angiogenesis, that is, excessive production of aberrant non-functional tumor vascular structures associated with reduced tumor growth." (PMID 25393540, 2014). "Return of functional vessels in treated tumours is then supressed by Dll4 mAb treatments." (PMID 24736631, 2014). "The surprising finding of these studies was that enforced activation of the Wnt/β-catenin pathway in these tumors led to reduced tumor angiogenesis by the up-regulation of Dll4 (Delta-like 4) and increased Notch signaling in endothelial cellls during tumor neoangiogenesis." (PMID 24590145, 2014). "However, Dll4 was found to be significantly correlated with tumor metastasis (P=0.012), tumor T-stage (P=0.023), tumor grade (P=0.033) and VEGFR-2 expression levels (P=0.001)." (PMID 25364440, 2014). "Covariables including patient characteristics (gender, age and body mass index (BMI)), tumor features (including tumor size, histological classification, grade, and T stage), and angiogenesis associated–factors (including MVD and DLL4 density) were all transformed into binary data." (PMID 24931473, 2014). "In conclusion, high Dll4 expression levels were demonstrated to be clearly associated with high VEGFR-2 expression levels, indicators of pathological aggressiveness (such as metastasis, pathological grade and tumor stage) and poor prognosis in CCRCC patients." (PMID 25364440, 2014). "Following these leads, we hypothesized that endothelial DLL4 may accelerate tumor progression by endothelial–tumor cell interactions." (PMID 24931473, 2014). "DLL4 signaling has been extensively reported to be critical for tumor angiogenesis." (PMID 24931473, 2014). "Moreover, a soluble form of DLL4 blocked tumor growth in both bevacizumab-sensitive and bevacizumab-resistant tumors by disrupting vascular function." (PMID 23898884, 2013). "Additionally, selective blocking of Notch1 with antibodies inhibits tumor growth by a mechanism consistent with that of Dll4 inhibition, namely by promoting abnormal growth of vessel sprouts that do not perfuse tissues." (PMID 23601498, 2013). "DLL4 was expressed in tumor endothelium, and thus the protein level of DLL4 increased in ccRCC." (PMID 23826258, 2013). "On the other hand, Dll4-driven Notch activation might reduce both tumor-induced angiogenesis and endothelial cell responsiveness to VEGF, and therefore argue rather for the use of Dll4 as an effective therapeutic approach in cancers." (PMID 23967403, 2013). "Thus, DLL4 expression in the tumor cells was functionally active, and appears to be consistent with our clinical data." (PMID 23898884, 2013).
tumor (continued). "We hypothesized that miRNA-30a might be a new regulator of DLL4 and might play an important role in angiogenesis and tumor progression." (PMID 23826258, 2013). "Indeed, Dll4/Notch activation reduces overall tumor angiogenesis, while tumor vascular function was improved and tumor growth was heightened." (PMID 23967403, 2013). "The DLL4-positive group had a greater depth of tumor invasion (p < 0.01, p < 0.01), more lymph node metastases (p < 0.01, p < 0.05), and significantly more venous (p < 0.05, n.s.)and lymphatic invasion (p < 0.01, p < 0.01 respectively) in not only the cancer cell but also stroma." (PMID 23898884, 2013). "Finally, the expression of miR-30a was correlated with DLL4 expression, tumor features (metastatic condition and microvessel density), and patient metastasis-free survival." (PMID 23826258, 2013). "However, in the present study, we found that high-level DLL4 was associated with high MVD in ccRCC, which was correlated with tumor hematogenous metastasis." (PMID 23826258, 2013). "Organ specificity in the evaluation of DLL4 expression of the tumor tissues should be considered." (PMID 23898884, 2013). "Thus, 90 cases of ccRCC and 28 cases of adjacent non-tumor tissues were collected to examine the expressions of miR-30a and DLL4." (PMID 23826258, 2013). "Blockade of Dll4-mediated Notch signaling has been described as a modulator of tumor angiogenesis." (PMID 23285048, 2012). "In addition, the study of SIRT1 knock-in mice indicated that SIRT1 functioned to maintain neovascularization capacity in response to DLL4 stimulation in the tumor vascular endothelium." (PMID 23028940, 2012). "Recently, several groups have investigated whether inhibition of the Dll4/Notch pathway might affect tumor angiogenesis and growth." (PMID 22279550, 2012). "Dll4 inhibition works by increasing vascular density through uncontrolled growth, resulting in the new vasculature being disorganized, inefficient and poorly perfused, leading to an increase in tumor hypoxia and reduction in tumor growth." (PMID 22279550, 2012). "Interference with Dll4 in several tumor models recapitulates what has been reported in development." (PMID 24213317, 2012). "The initial speculation of DLL4 signaling involvement in tumor angiogenesis came from expression analyses of DLL4." (PMID 21824400, 2011). "In addition, we also demonstrate that specifically modulating Dll4 expression on BM-VPC is sufficient to affect vascular stability of tumor vessels during a restricted period throughout tumor development." (PMID 21483741, 2011). "The combination of blocking DLL4 in tumor and vascular cells was shown to have an additive effect." (PMID 21831306, 2011). "Several tip cell-enriched genes have recently been identified in the mouse retina which may yield clues to which signaling pathways mediate the effects of Dll4-Notch blockade on the tumor vasculature." (PMID 21923938, 2011). "Thus, blockade of Dll4-Notch signaling leads to tumor vessel "abnormalization" (i.e. the formation of a hypersprouting, non-functional vasculature) with resultant growth inhibitory effects on tumors." (PMID 21923938, 2011). "Indeed previous studies have shown that tumor treatment with Dll4 inhibitor inhibits tumor growth by promoting non productive angiogenesis." (PMID 22087289, 2011). "Importantly, inhibition of DLL4 not only reduced tumor growth but also reduced tumor initiating cells as shown by serial transplantation experiments." (PMID 21831306, 2011). "DLL4 acting through Notch1 and Notch4 appears to play key roles regulating endothelial cells and bone marrow-derived endothelial cell progenitors during normal and tumor angiogenesis." (PMID 21831306, 2011). "Indeed, tumor vascular histology and imaging studies have revealed a shift to smaller vessel calibers and inefficient blood flow in anti-DLL4 treated tumors (unpublished observations)." (PMID 21824400, 2011).
tumor (continued). "As Dll4 inhibitors are entering clinical cancer trials, this review aims to provide current perspectives on the function of the Dll4-Notch signaling axis during tumor angiogenesis and as a target for anti-angiogenic cancer therapy." (PMID 21923938, 2011). "In addition to its role in the tumor vasculature, evidence has accumulated indicating an important role for DLL4-Notch signaling in tumor cells." (PMID 21831306, 2011). "In addition to tumor studies using anti-DLL4 as a single agent, additive anti-tumor activity was observed in combination with anti-VEGF therapy in a majority of tested tumor models." (PMID 21824400, 2011). "The most pronounced effects were observed at the highest doses, which may be beyond what is needed for blocking Dll4 in tumor vessels in clinical settings." (PMID 21923938, 2011). "Since angiogenic sprouting after DLL4 blockade remains a VEGF-dependent process, DLL4 inhibition may increase the dependency of the tumor microvasculature on a VEGF-mediated survival signal." (PMID 21824400, 2011). "Tumor-derived exosomes were also found to incorporate the Notch ligand Delta-like 4 (Dll4) and transfer the Dll4 protein into the cell membrane of host endothelial cells, resulting in the inhibition of Notch signaling and the switch of endothelial cell phenotype toward tip cells." (PMID 22190973, 2011). "In addition to a role in tumor angiogenesis, Dll4-Notch signaling also plays a crucial role in T-cell lymphocyte development and differentiation." (PMID 21923938, 2011). "For that we increased the number of circulating BM-VPC by administering mouse BM-VPC derived from Dll4GOF mice with induced Dll4 over-expression (mDll4GOF BM-VPC) or normal Dll4 expression (WT BM-VPC) after tumor establishment during a restricted period of time." (PMID 21483741, 2011). "In addition, we noted loss of ASMA-positive cells around the blood vessels, which previously has been seen after endothelial specific knockout of Jagged-1 or after Dll4 blockade during tumor angiogenesis." (PMID 21533193, 2011). "Two major changes following DLL4/NOTCH1 blockade might contribute to the defective function of the tumor vasculature: impairment of lumen formation and promotion of a chaotic vascular network." (PMID 21824400, 2011). "Consequently, transplantation of BM-VPC with decreased Dll4 resulted in impaired tumor angiogenesis, increased tumor hypoxia and apoptosis, and decreased tumor growth." (PMID 21483741, 2011). "Thus, it is plausible that some of these additional factors also act upstream of Dll4 in the tumor environment." (PMID 21923938, 2011). "DLL4 blockade could worsen the already impaired vascular communication in the tumor microvascular network and lead to exacerbated functional shunting, a suspected primary cause of dysfunctional microcirculation and local hypoxia in cancer." (PMID 21824400, 2011). "Therefore it appears plausible that Notch1 is also the predominant mediator of Dll4-Notch signaling in the tumor vasculature, although Notch4 has also been described as a receptor specifically expressed by endothelial cells." (PMID 21923938, 2011). "It is also possible that such anti-Notch antibodies may have value as inhibitors of stromal activities that support tumor cell growth, such as angiogenesis, which depends on a DLL4-Notch1 signaling axis." (PMID 20161710, 2010). "Finally, in addition to improved anti-tumor efficacy, simultaneous blockade of Dll4/Notch and Ephrin-B2/EphB4 abolished the liver vascular lesions seen when only Dll4/Notch is inhibited." (PMID 21092311, 2010). "Therefore, combinational targeting Dll4/Notch signaling EphrinB2-EphB4 has greater efficacy in blocking vessel maturation and perfusion of the tumor." (PMID 21092311, 2010). "For instance, DLL4-dependent events, such as tumor neoangiogenesis, may be relatively insensitive to the LBD antibodies reported here." (PMID 20161710, 2010).